INS (insulin)
Diseases named in the same sentence as INS in open-access papers (continued):
Sharing a sentence is not in itself a finding about the gene and the disease.
Hypertension (continued). "Logistic regression analysis showed that the CVDs was associated with hypertension (OR: 2.41; 95% CI: 1.11-5.22; p=0.026), hypolipidemia treatment (OR: 2.20; 95% CI: 1.06-4.59; p=0.034), insulin use (OR= 0.39; 95%CI: 0.15-0.96, p=0.043) and LDL-C (OR: 1.01; 95% CI: 1-1.02; p=0.035) in T2DM patients." (PMID 35655685, 2022). "Risk factors for the development of hypertension were also assessed in 278 normotensive women over a 12-year follow-up, reporting that fasting plasma insulin concentrations predicted transition from normal to high blood pressure independent of baseline body mass and weight changes." (PMID 36289636, 2022). "Gestational diabetes stems from dysregulation of insulin and altered fatty acid metabolism while hypertension and preeclampsia may arise from underlying kidney disease or changes in the renin–angiotensin or sympathetic nervous systems." (PMID 36615797, 2022). "The association of TL shortening with hypertension, dyslipidaemia and defects in insulin secretion in PLWH on ART in South Africa suggests that TL may be used as an early biomarker of these CMDs in this population." (PMID 35119008, 2022). "In addition, alterations in Na+,K+ -ATPase expression and function has been associated with hypertension, inflammation and the control of insulin and the development of painful diabetic polyneuropathy." (PMID 36291108, 2022). "The etiological factors of arterial hypertension include: hemodynamic disorders accompanying obesity and an increase in peripheral vascular resistance associated with endothelial dysfunction, insulin resistance and the influence of adipokines released from adipose tissue." (PMID 35055447, 2022). "We have demonstrated that insulin sensitivity in pregnancy is inversely associated with systolic and diastolic blood pressure as well as hypertension 10–14 years postpartum, even after adjustment for multiple confounders from pregnancy including BMI and blood pressure (MAP, SBP and DBP)." (PMID 33536549, 2022). "In addition to these factors, long-term arterial hypertension, high daily insulin doses, eGFR, and L-citrulline were associated with CAS." (PMID 35011813, 2021). "In turn, this may reduce multiple cardiometabolic risk factors including cholesterol, hypertension, and insulin sensitivity." (PMID 34371975, 2021). "In addition to these factors, lower BMI, long-term arterial hypertension, high insulin dose, and reduced eGFR are associated with CAS." (PMID 35011813, 2021). "Insulin could cause hypertension through stimulation of the sympathetic nervous system, an increase in renal sodium retention, modulation of calcium transport, and consequent induction of hypertrophy of vascular smooth muscle." (PMID 34501843, 2021). "The second aim of this study was to analyze changes of basal components of RAAS system, of glucose metabolism, and of insulin sensitivity in obese subjects after bariatric surgery; the third aim was to develop predictive models of persistence of diabetes and of hypertension in spite of weight loss." (PMID 34107965, 2021). "Accordingly, it is difficult to conclude definitively that this particular OSV pattern is beneficial for childhood because consumption of a salt-rich dietary pattern should increase the risk of high blood pressure and higher sugar intake increases fasting glucose and insulin resistance." (PMID 33807269, 2021). "The etiology of the frequent hypertrophic cardiomyopathy in lipodystrophy remains unclear; in part, it could be related to the underlying hypertension, but also to the increased growth stimulatory action of excess insulin." (PMID 32117065, 2020). "Compared with the insulin group, the switching group had a similar risk of primary cesarean section, pregnancy-related hypertension, preeclampsia, preterm birth, very preterm birth, low birth weight, high birth weight, large for gestational age, and congenital malformations." (PMID 32887578, 2020).
Hypertension (continued). "Insulin’s anabolic action may contribute to weight gain, which independently associates with sympathoactivation and arterial hypertension." (PMID 33292431, 2020). "It is still under debate if insulin has a causal effect on hypertension under normoglycemia." (PMID 32850773, 2020). "Knowing that SB and hypertension are associated with PC in the literature, SB can increase adiposity and, therefore, increase the risk of developing PC through high levels of sex hormones, insulin resistance and chronic inflammation." (PMID 33050163, 2020). "These multiple-associated phenotype classes were associated with two (insulin/height, body mass index/C-reactive protein, smoking/myocardial infarction, hypertension/smoking) and three (smoking/LDL-C, hemoglobin/hematocrit, smoking/alcohol consumption) variants each." (PMID 31891604, 2019). "Moreover, treatment with 10% fructose in drinking water induced hypertension in Wistar rats, which was associated with elevated levels of plasma insulin, glucose and triglycerides." (PMID 30737597, 2019). "Medication use, alcohol consumption, and smoking status are recognized as potential covariates that may influence energy intake, hypertension risk, and insulin sensitivity." (PMID 30972022, 2019). "High cholesterol level impacts β-amyloid formation in the brain; abnormal insulin function, a key factor of T2D and related disorders, increases the risk for AD; cardiovascular risk factors such as high cholesterol and hypertension are common to T2D and AD." (PMID 31404401, 2019). "Likewise, the positive association of baseline fasting insulin, HOMA-IR, and insulin-glucose ratio (IGR) with incident hypertension among an Iranian population has been previously reported." (PMID 31728151, 2019). "The inverse association between UCP2 expression levels in PBC and uric acid levels is also of interest regarding the relevance of uric acid levels in relation to cardiometabolic risk factors, particularly high blood pressure and elevated insulin and triglycerides." (PMID 31064394, 2019). "Last, during the follow-up period, children became adolescents or young adult, so their hormones may have caused transient or physiological insulin resistance, leading to the changes in blood pressure and occasional hypertension." (PMID 29093301, 2018). "In other words, the development of impaired insulin metabolic signaling and endothelial function can be promoted by excess circulating aldosterone, and sequentially contributes to hypertension and associated cardiovascular and renal structural and functional abnormalities." (PMID 30332741, 2018). "However, it will determine, in the medium/long term, several critical alterations in metabolism (insulin resistance, overweight, etc.), cardiovascular system (hypertension), loss of performance, GIT events, reproduction/sexual repercussions, etc.." (PMID 30304113, 2018). "An analysis assessing treatment effect on the primary end point adjusted for BMI, number of medications at baseline, 10-year Framingham risk score, basal insulin level at baseline, and duration of hypertension found similar results with a rate ratio of 6.4 (95% CI, 3.1–13.0; P<0.001)." (PMID 29133606, 2018). "In obese dogs, hypertension can occur by different mechanisms including the activation of the renin-angiotensin-aldosterone axis, hyperadrenergic activation and insulin resistance causing hyperadrenergic activation, and increased production of angiotensin and proinflammatory cytokines." (PMID 28058131, 2016). "Other variables (at baseline) were gender, age, heart failure, renal failure, depression, asthma/chronic obstructive pulmonary disease, hypertension, dyslipidaemia, insulin, smoking, admission for cardiovascular causes, pills per day, walking habit, fasting blood glucose and creatinine." (PMID 26056618, 2015).
Hypertension (continued). "In addition, we only included patients naïve to insulin therapy in our analyses to reduce the confounding effect of insulin therapy on weight and cardiovascular risk factors such as hypertension." (PMID 25361574, 2014). "First, we could not include several possible confounding variables that are known hypertension risk factors, such as plasma insulin, family history, alcohol and salt consumption, smoking, waist circumference, and socioeconomic status." (PMID 24360336, 2013). "The authors then suggested that an imbalance between the release of both substances may be involved in pathophysiology of hypertension and atherosclerosis in insulin-resistant states associated with endothelial dysfunction." (PMID 23573411, 2013). "However, the evidence was also controversial, with a strong and null association between hypertension and insulin." (PMID 24281091, 2010). "Therefore insulin is a good candidate for salt-sensitive hypertension, as it has been implicated in both hypertension and sodium retention." (PMID 20886000, 2010). "The association between the insulin gene, INS, and hypertension has been well documented." (PMID 20886000, 2010). "In conclusion, our findings show that Hashimoto's thyroiditis is associated with increased arterial wall IMT regardless of thyroid function and well-known cardiovascular risk factors, such as abdominal obesity, hypertension, fasting glycemia, serum insulin and lipid levels." (PMID 20509904, 2010). "In the cases of hypertension associated with IR/Hyperin, probably, a combination treatment of hypertensive drugs with insulin-sensitizing drugs could improve blood pressure control by reducing insulin levels which in themselves can be a cardiovascular risk factor." (PMID 41463109, 2025). "Thus, given the close association between hypertension and microvascular disease, an increase in WS—reflecting improved vascular dilation and enhanced insulin sensitivity—may serve as a robust predictor of hypertension risk." (PMID 41121592, 2025). "However, many studies showed that the presence of CAH is associated with an increased risk of weight gain, worsening of insulin sensitivity, high blood pressure, endothelial dysfunction, early atherosclerotic changes in the vascular wall, and left ventricular diastolic dysfunction." (PMID 39240753, 2025). "Finally, when adjusted for age, BMI, smoking status, and reimbursement for hypertension and diabetes, the following biomarkers were nominally associated with incident AS: systolic blood pressure, fasting plasma insulin and proinsulin, OGTT 30 min plasma proinsulin, and serum C-peptide." (PMID 39593205, 2024). "The study of the functional relationship between insulin and renin-angiotensin signaling systems, which play a key role in the control metabolism and homeostasis, seems particularly important due to the confirmed clinical association between IR and hypertension." (PMID 38323106, 2024). "A growing body of literature using longitudinal and experimental designs supports the fact that PA may be a strategy to maintain or improve smell, with potential mechanisms including reduced hypertension, reduced cell and neurotransmitter loss, and hormonal modulation including insulin sensitivity." (PMID 38903386, 2024). "In addition, during the course of AS, IL-6 interacts with the hypothalamic-pituitary-adrenal (HPA) axis, leading to traditional cardiovascular risk factors including decreased insulin sensitivity, increased BMI, and the occurrence of hypertension, exacerbating atherosclerosis." (PMID 38988836, 2024). "It has been suggested that bariatric surgery-related hypertension remission is caused by reduced inflammatory reactions and improved insulin resistance that could lessen arterial stiffness and sodium reabsorption with subsequent normalization of blood pressure levels." (PMID 37178225, 2023).
Hypertension (continued). "Some other research indicates an impact of other polymorphisms of other genes on the course of acromegaly, which could have an impact on the development of early atherosclerosis, determine higher plasma insulin concentration, higher BMI, hypertension, or increased risk of osteoporosis." (PMID 37446150, 2023). "Poor glycemic control was significantly associated (p<0.05) with insulin use, fasting glucose ≤70 and ≥100 mg/dl, postprandial glucose ≥180 mg/dl, no physical activity, the interaction between age group ≤59 years and the time of disease diagnosis >10 years, and presence of arterial hypertension." (PMID 35891859, 2022). "This may be due to an effect of prenatal growth on the pathogenesis of early disease, by “programming” the development of risk factors (e.g., insulin/glucose metabolism, hypertension, and lipid metabolism) or due to altered “stability” of established physiological conditions." (PMID 35402571, 2022). "Insulin sensitivity during pregnancy was associated with all blood pressure outcomes at follow-up, and although attenuated after adjustments, remained statistically significant (hypertension OR 0.79, 95%CI 0.68– 0.92; SBP beta −0.91, 95% CI −1.34– −0.49; DBP beta −0.50, 95% CI −0.81– −0.19)." (PMID 33536549, 2022). "In addition, various genes that regulate the renin-angiotensin system and adrenergic system, estradiol, testosterone, estrogen/androgen ratio, and environmental factors such as age, BMI, insulin, oxidative stress, and cholesterol affect the risk of hypertension among postmenopausal women." (PMID 36003912, 2022). "Thus, similar to SHR, sodium dependence of hypertension in fructose-fed rats could be related to the loss of the loop mechanism that limits insulin-induced antinatriuresis when extracellular fluid volume is expanded by high-sodium feeding." (PMID 36289636, 2022). "Blood insulin might contribute to the synthesis of collagen protein and stimulate hyperplasia and hypertrophy of smooth muscle cells of the blood vessels, thus resulting in a higher risk of hypertension in subjects with MetS." (PMID 33997011, 2021). "Through the impairment of the PI3-K insulin pathway, IR plays a key role in the development of metabolic dysfunction and underlies a cluster of cardiovascular and metabolic abnormalities referred to as the metabolic syndrome (including hypertension, dyslipidaemia and dysglycaemia)." (PMID 33430419, 2021). "Furthermore, medications such as antidepressants, diabetes treatments (insulin), oral contraceptives, and hypertension medicines are also associated with maternal obesity; the strength of the associations, varies depending on individual response to the medication." (PMID 34368253, 2021). "TMAO is associated with cholesterol metabolism, insulin resistance, platelet aggregation, thrombosis, vascular inflammatory response, and atherosclerotic plaque formation, which may lead to atherosclerosis, heart failure, hypertension, and stroke." (PMID 33195447, 2020). "Microvascular changes because of hypertension may cause a reduction in insulin sensitivity by reducing the skeletal muscle uptake of glucose, whereas microvascular changes resulting from excessive adiposity may increase peripheral vascular resistance and, consequently, blood pressure." (PMID 32396192, 2020). "Additionally, sympathetic activity increases in response to the raised insulin, which may cause hypertension in those who are obese." (PMID 28282859, 2017). "In the PT, IRS2-mediated pathway is preserved and the stimulation of sodium reabsorption by insulin causes sodium retention and possibly subsequent hypertension, whereas the potential impairment of the IRS1-mediated pathway could lead to unsuppressed gluconeogenesis." (PMID 27247938, 2016). "In addition, high levels of insulin increase sodium reabsorption favouring expansion of extracellular fluid volume, which may predispose to hypertension." (PMID 23573411, 2013).
Hypertension (continued). "Moreover, it has been shown that a chronically elevated heart rate may cause vasoconstriction, arterial stiffening and insulin resistance, all resulting in hypertension." (PMID 22701740, 2012). "By integrating three critical dimensions—glycemic control (HbA1c), vascular health (hypertension status), and central adiposity (waist circumference)—eGDR captures a comprehensive insulin sensitivity phenotype that extends beyond simple glucose metabolism." (PMID 41601911, 2026). "SHapley Additive exPlanations analysis revealed gender, poverty-to-income ratio, sleep duration, smoking status, educational levels, race, age, high cholesterol, hypertension, and insulin use as the most influential predictors." (PMID 41650107, 2026). "Insulin sensitivity was quantified using eGDR, calculated from waist circumference, hypertension status, and hemoglobin A1c levels." (PMID 40538401, 2025). "These include haemodynamic factors such as hypertension and glomerular hyperfiltration, but also extend to the chronic inflammatory milieu, insulin resistance, and adipokine dysregulation." (PMID 40391013, 2025). "As a surrogate for insulin sensitivity, eGDR integrates visceral obesity (via WC), hypertension, and hemoglobin A1c, reflecting the synergistic effects of adiposity, chronic inflammation, and oxidative stress on cardiovascular and renal systems 20-22." (PMID 40959566, 2025). "Nifedipine, an L-type calcium channel blocker frequently used for the treatment of hypertension, can also impair insulin sensitivity and secretion." (PMID 39763275, 2025). "Clinically, 67% of the total population had hypertension, 60% used insulin, 33% were obese, 20% were mobility-dependent, 7% were smokers, and 33% consumed alcohol." (PMID 40574084, 2025). "The naïve Bayes model incorporated HDL-C, ALB, DM, total bilirubin, creatinine, hypertension, TC, fasting insulin, age, PLT, height, sex, BMI, uric acid, ALT, TG, body weight, HbA1c, LDL-C, and AST." (PMID 40361915, 2025). "The burden of hypertension, oedema, poor glycaemic control requiring insulin, and prolonged QTc intervals was higher among HS than NHS throughout the two years." (PMID 40084715, 2025). "In the DI-GM group, there was no statistically significance differences in gender, marital status, physical activity, prevalence of hypertension, prevalence of coronary heart disease, prevalence of stroke, and insulin usage status." (PMID 40896191, 2025). "In multivariable models, insulin use and hypertension were balanced across CRP quartiles in our cohort, suggesting they did not drive the association." (PMID 41159344, 2025). "On the other hand, hypertension itself can, in turn, worsen insulin sensitivity through vascular stiffness and neurohormonal activation." (PMID 41463109, 2025). "The results showed that the serum A20 level, duration of T2DM, hypertension, use of insulin and GLP-1 receptor agonists were positively correlated with lumbar spine 1-4 BMD and FPG was negatively correlated with lumbar spine 1-4 BMD (P<0.1)." (PMID 40078583, 2025). "Cortisol is known to impair insulin sensitivity and contribute to hypertension, a condition that disproportionately affects young and middle-aged Black adults." (PMID 40871668, 2025). "The eGDR is a simple and non‐invasive measure of insulin sensitivity based on waist circumference, hypertension and HbA1c, which can also be used in people with T1DM." (PMID 40083078, 2025). "The potential mechanisms linking AIP and hypertension are still under further investigation, but they are inclined towards factors such as lipid deposition, insulin resistance, adipokine secretion, and autonomic nervous system dysfunction." (PMID 39869615, 2025). "Both RYGB and SG are quite effective at lowering body weight and improving metabolic parameters such as glucose regulation, insulin sensitivity, and hypertension control." (PMID 40430186, 2025).